DMD (dystrophin)
Diseases named in the same sentence as DMD in open-access papers (continued):
Sharing a sentence is not in itself a finding about the gene and the disease.
hypertrophic cardiomyopathy (4 papers, 2022 to 2025). A condition in which the myocardium is hypertrophied without an obvious cause. "Similarly, patients with combined DMD and myosin heavy chain 7 (MYH7) variants demonstrate unique mixed-cardiac phenotypes, showing features of both dilated and hypertrophic cardiomyopathy." (PMID 40134720, 2025). "“Hypertrophic cardiomyopathy” in the signal pathway was followed with the p.adjust value of 1.10×10-3 and the corresponding collective action gene set with mutations included 8 genes: IGF1, CACNA1S, MYH7, IL6, TTN, CACNB2, LAMA2, DMD." (PMID 37876543, 2023).
lung adenocarcinoma (4 papers, 2021 to 2025). A carcinoma that arises from the lung and is characterized by the presence of malignant glandular epithelial cells. "We next checked the gene expression of DMD in the TCGA—Lung adenocarcinoma (LUAD) and TCGA—Lung squamous cell carcinoma (LUSC) cohorts." (PMID 34945000, 2021).
macroglossia (4 papers, 2011 to 2024). The presence of an excessively large tongue, which may be congenital or may develop as a result of a tumor or edema due to obstruction of lymphatic vessels, or it may occur in association with hyperpituitarism or acromegaly. "Recently, a 6-month-old pig with macroglossia at a slaughterhouse was found to have severely reduced dystrophin staining and a pseudoexon insertion was reported." (PMID 36834603, 2023). "Such phenotypes include Muscle dystrophy, Camptodactyly, Generalized amyotrophy, Macroglossia, Myopathy, Rimmed vacuoles, Muscle fiber splitting, Skeletal muscle atrophy, Abnormal muscle, and fiber dystrophin expression." (PMID 32019583, 2020). "We describe a patient of DMD with isolated macroglossia with 271 bp deletion in exon 50 of the dystrophin gene and speculate a relationship in this regard." (PMID 21655206, 2011).
mesenchymal tumors (4 papers, 2014 to 2023). "Copy number losses or translocations encompassing the DMD gene have been described as a recurrent event in canine OS, and losses of DMD sequences have been suggested as a mechanism throughout human mesenchymal tumors evolve to more severe cases." (PMID 37445641, 2023). "Striking similarities exist between DMD aberrations noted in our canine OS population and those reported in human mesenchymal tumors of myogenic origin." (PMID 31341965, 2019). "It has been demonstrated that DMD is sensitive to the replication stress on DNA damage and genome instability in tumor cells and may act as a tumor suppressor involved in the development and progression of mesenchymal tumors." (PMID 30909962, 2019).
metastatic tumors (4 papers, 2014 to 2025). "Deletion was significantly associated with a decrease in DMD expression (p = 0.002), independently of gender (53.7% of men vs. 46.3% of women), but was significantly more frequent in metastatic tumors (Chi2 = 2.68 × 10−4)." (PMID 31266185, 2019). "Similarly, distinct mutational patterns emerged between primary and metastatic tumors, with DMD and KMT2D more prevalent in primary tumors, while SAMD9L and ATP8B1 were found in metastases." (PMID 41590495, 2025). "Deletions of dystrophin in KIT/PDGFRA mutant GIST have been previously reported and usually are associated with more advanced clinical stages of disease such as metastatic tumors." (PMID 29510530, 2018). "Our study confirms the presence of DMD deletions only in KIT/PDGFRA mutant GIST and this event is almost associated with metastatic disease." (PMID 25143820, 2014).
muscular atrophy (4 papers, 2017 to 2024). The loss of muscle tissue due to inactivity or disease. "Dysfunction of dystrophin, a key protein for muscles, can cause DMD, associated with damaged muscle fibers and muscular atrophy." (PMID 29593571, 2018).
myotonic dystrophy type 1 (4 papers, 2014 to 2025). Steinert disease, also known as myotonic dystrophy type 1, is a muscle disease characterized by myotonia and by multiorgan damage that combines various degrees of muscle weakness, arrhythmia and/or cardiac conduction disorders, cataract, endocrine damage, sleep disorders and baldness. "In a study of myotonic dystrophy type 1 (DM1), a neuromuscular disease in which altered RNA splicing factors deregulate alternative splicing, it was shown that DMD exon 78 is abnormally spliced in patients’ muscles." (PMID 38802640, 2024). "DMD (B = 1.748, S.E.=0.794, p =0 .028, OR = 5.744), but not Steinert disease (B = 0.388, S.E.=0.801, p = 0.628, OR = 1.474), significantly predicted anxious/depressive symptoms." (PMID 38685111, 2024).
rhabdomyolysis (4 papers, 2021 to 2025). Necrosis or disintegration of skeletal muscle often followed by myoglobinuria. "However, rhabdomyolysis may occur in the absence of succinylcholine intraoperatively and during postoperative cardiac arrest as a result of hyperkalemia in patients with DMD." (PMID 39931560, 2025).
scoliosis (4 papers, 2014 to 2026). A congenital or acquired spinal deformity characterized by lateral curvature of the spine. "The multidisciplinary assessment of patients with DMD requiring treatment for scoliosis is reviewed, with particular focus on bone, cardiac and respiratory health." (PMID 41899042, 2026).
soft tissue sarcoma (4 papers, 2019 to 2022). A malignant neoplasm arising from muscle tissue, adipose tissue, blood vessels, fibrous tissue, or other supportive tissues excluding the bones. "In conclusion, we observed that DMD was frequently deleted in soft tissue sarcomas and that this deletion was significantly associated with metastatic progression." (PMID 31266185, 2019). "In addition, reports of several patients with soft-tissue sarcomas indicate a role of the DMD gene and especially of intragenic deletions, in the development of this type of cancer." (PMID 35790299, 2022). "Given the canonical role of dystrophin in muscle, it is unsurprising that a large body of evidence for a role for DMD in cancer comes from soft tissue sarcomas (STS), and the myogenic tumours in particular." (PMID 33188621, 2021).
Ventricular arrhythmia (4 papers, 2019 to 2025). "Both in vivo and ex vivo data indicated that activation of dystrophin transcription reduced the susceptibility to ventricular arrhythmia of lncDach1-TG mice." (PMID 39773412, 2025). "We found that lncDach1 inhibited the membrane trafficking of Nav1.5 by binding to dystrophin, which led to reduced sodium current and increased ventricular arrhythmia susceptibility." (PMID 39773412, 2025). "Given that DMD patients and dKO mice are at risk for ventricular arrhythmia leading to sudden cardiac death, we therefore searched for such defects in dKO mice treated with AAV micro-dystrophin." (PMID 40562489, 2025). "The conservative fragment of lncDach1 inhibited membrane distribution of dystrophin and Nav1.5, and promoted the inducibility of ventricular arrhythmia." (PMID 39773412, 2025). "It has been suggested that changes in the functional expression of Na and K ion channels associated with a specific mutation in the dystrophin gene lead to QRS widening and QTc prolongation that can be seen in patients with DMD and play a role in the formation of ventricular arrhythmias." (PMID 37510124, 2023). "Strikingly, activation of Dystrophin transcription by dCas9-SAM system in lncDach1-TG mice rescued the impaired membrane distribution of dystrophin and Nav1.5, and prevented the occurrence of ventricular arrhythmia." (PMID 39773412, 2025).
viral infection (4 papers, 2009 to 2025). "Abnormal dystrophin has also been identified as a potential susceptibility gene for viral infection of the myocardium." (PMID 20492678, 2010). "Specific enterovirus expressed proteases (2Apro and 3Cpro) appear also to be correlated with the persistence of viral infection and tropism for cardiac proteins (e.g., dystrophin)." (PMID 40558663, 2025). "Synthetic oligonucleotides are being developed as therapies for a broad range of diseases, including hypertriglyceridemia, viral infections and to induce dystrophin exon skipping for DMD." (PMID 29045431, 2017). "Cleavage of dystrophin may have a role in release of the virus from myocyte since viral infection is increased in the absence of dystrophin." (PMID 20436849, 2009).
adrenal hypoplasia (3 papers, 2021 to 2025). "Furthermore, the X chromosomal location of the DMD and congenital adrenal hypoplasia genes are adjacent, suggests a possible mechanistic connection between DMD and adrenal insufficiency." (PMID 39715964, 2025). "In addition, a gene variation that causes congenital adrenal hypoplasia, NR0B1 (encoding DAX1), is adjacent to the DMD gene on the X chromosome, providing a potential mechanistic link between DMD and adrenal insufficiency." (PMID 36036925, 2022).
atrial fibrillation (3 papers, 2022 to 2024). A disorder characterized by an electrocardiographic finding of a supraventricular arrhythmia characterized by the replacement of consistent P waves by rapid oscillations or fibrillatory waves that vary in size, shape and timing and are accompanied by an irregular ventricular response. "A study reported that atrial-specific upregulation of miR-31 in human atrial fibrillation is an important mechanism that causes atrial loss of dystrophin and neuronal nitric oxide synthase; this loss leads to the electrical phenotype induced by atrial fibrillation." (PMID 36123601, 2022). "A reduction in both dystrophin and neuronal nitric oxide synthase (NOS1) secondary to microRNA-31 (miR-31) up-regulation contributes to the atrial electrical remodelling that underpins human and experimental atrial fibrillation (AF)." (PMID 38270932, 2024).
colorectal cancer (3 papers, 2022 to 2023). A primary or metastatic malignant neoplasm that affects the colon or rectum. "For example, the fact that miR-31-5p has been reported to be dysregulated in cystic pancreatic lesions has also been investigated in colorectal cancer patients, and it was demonstrated that the structural regulation of the miR-31-5p-dystrophin axis was altered in CRC patients." (PMID 35954223, 2022). "Thus, the dysregulation of the miR-31-5p-DMD axis may be a novel biomarker for predicting the development and prognosis not only of sporadic early-onset colorectal cancer, but also of cystic pancreatic neoplasms." (PMID 35954223, 2022). "Our method is able to identify the known cancer drivers and further nominate candidates that exhibit higher breakpoint proximity than expected by random chance, such as DMD and LRRN3 in esophageal cancer, NF1 in ovarian cancer, CDK12 in uterine cancer, and WWOX in colorectal cancer." (PMID 36163358, 2022).
COVID-19 (3 papers, 2021 to 2022). A disease caused by infection with severe acute respiratory syndrome coronavirus 2. "The results of Cox analysis revealed that the RACGAP1, TCF7L2, IRF7, DMD, and JUN were significantly associated with the development of COVID-19/BRCA (p < 0.05)." (PMID 36060002, 2022). "In this study, we found 14 other diseases associated with COVID-19 by sharing four DEGs (i.e., DMD, C2CD3, WNT3, and AHDC1) most prevalent in COVID-19." (PMID 36059456, 2022). "In addition, we identified 14 other diseases associated with COVID-19 by sharing four DEGs (i.e., DMD, C2CD3, WNT3 and AHDC1) which were most prevalent in COVID-19." (PMID 36059456, 2022). "Independent prognosis and survival analysis revealed important differential genes, including RACGAP1, TCF7L2, IRF7, DMD, and JUN, which can be used as effective biomarkers for screening and characterizing patients with BRCA and COVID-19 at all stages." (PMID 36060002, 2022). "Five (9.43%) were COVID-19 positive with mild symptoms of respiratory infection and anosmia; 23 (42.6%) were vaccinated, but in almost 20% of DMD families, none of the family members was vaccinated." (PMID 35010666, 2021).
diabetes (3 papers, 2015 to 2024). "MAST1 is an important paralog of MAST245, and phosphorylation of DMD or UTRN may modulate their affinities for associated proteins, and thus may also be associated with diabetes mellitus." (PMID 26399914, 2015).
dysferlinopathy (3 papers, 2017 to 2022). "NOX4-expressing PDGFRα+ cells were also found in the muscles of mice that model limb-girdle MD 2B (LGMD2B) (dysferlinopathy) and LGMD2F (δ-sarcoglycan deficiency); therefore, these observations are not restricted to dystrophin-deficient muscle." (PMID 36278481, 2022). "The absence of labeling for dysferlin and the rod domain and C-terminus of dystrophin in FFPE sections was documented in all three DMD patients (patients 4, 6, and 8) and the dysferlinopathy patient (patient 3), allowing a diagnosis to be made using FFPE sections." (PMID 28219397, 2017).
dyslipidemia (3 papers, 2021 to 2022). "We have recently demonstrated that loss of dystrophin, another sarcolemmal rigidity protein that causes Duchenne or Becker MD when mutated, results in a new type of primary genetic dyslipidemia both in patients and unmedicated mutant animals." (PMID 34366880, 2021). "From a clinical perspective, we also reported primary dyslipidemia, including elevated total cholesterol (CHOL) and triglyceride (TG) levels in dystrophin-deficient DMD patients, unmedicated DMD dogs, and heterozygous female carriers." (PMID 36447272, 2022). "We have recently demonstrated in typically mild dysferlin- and dystrophin-deficient mouse models that increased plasma cholesterol levels severely exacerbate muscle wasting, and that DMD patients display primary dyslipidemia characterized by elevated plasma cholesterol and triglycerides." (PMID 36447272, 2022). "The authors show compelling evidence that lack or reduced levels of dystrophin may lead to dyslipidemia in humans and dogs." (PMID 34155298, 2021).
ischemia (3 papers, 2015 to 2019). A hypoperfusion of the BLOOD through an organ or tissue caused by a PATHOLOGIC CONSTRICTION or obstruction of its BLOOD VESSELS, or an absence of BLOOD CIRCULATION. "Insertion of a mini-dystrophin gene via a dual adeno-associated viral vector which increases mini-dystrophin expression and restores nNOS at the sarcolemma, has also been shown to improve contraction-induced ischemia and mitigate the loss of force production and muscle damage." (PMID 28545481, 2017). "Further, dystrophin R16/17-mediated sarcolemmal nNOS recovery prevented functional ischemia, improved muscle force and enhanced exercise performance." (PMID 31266455, 2019). "miR-31 might have different roles; it is strongly induced in ischemia damaged myofibers, it plays a fundamental role in postnatal vascular repair, regulates both dystrophin expression and the progression of satellite cells toward differentiation." (PMID 25999854, 2015).
lung carcinoma (3 papers, 2009 to 2021). "The mutation profile in exons of the DMD gene in 3163 lung cancer samples was analysed in data from the cBioPortal for Cancer Genomics." (PMID 34945000, 2021). "Our study revealed that genetic variation in DMD (either as germline variants or as somatic mutations) could be associated with sex-specific risk of lung cancer." (PMID 34945000, 2021). "We further analysed the effect of the differential expression of DMD on 1424 lung cancer patients in 13 microarray datasets." (PMID 34945000, 2021). "However, the contribution of DMD to lung cancer susceptibility remains unclear." (PMID 34945000, 2021). "The results showed that the mRNA expression levels of DMD were significantly decreased in the lung cancer tissues compared with the control tissues." (PMID 34945000, 2021). "We also observed that DMD was differentially expressed in lung cancer subtypes curated in the Cancer Genome Atlas database." (PMID 34945000, 2021). "Consistent with previous findings, abnormal DMD expression was found in lung cancer compared with control tissues." (PMID 34945000, 2021). "The occurrence of DMD alterations varied across the studies/tumor types, but it was consistent for some tumor types such as breast and lung cancers." (PMID 27391342, 2017). "While all ISs in the lung cancer dataset showed positive signs in the normal lung and lung cancer samples, the ISs of 23 pairs in the DMD dataset showed the opposite signs of the normal muscle and DMD samples." (PMID 19371436, 2009). "Of these, DMD was differentially expressed in lung cancer cases curated in The Cancer Genome Atlas." (PMID 34945000, 2021). "This suggests different degrees of perturbation of gene expression between lung cancer and DMD." (PMID 19371436, 2009). "Therefore, we focused on investigating the potential effect of DMD expression on lung cancer." (PMID 34945000, 2021). "Based on gene annotation, expression analysis, co-expression analysis, and functional analyses, our findings support the hypothesis that DMD is abnormally expressed in cancer tissue and DMD-induced immune dysregulation may be responsible for the etiology of lung cancer." (PMID 34945000, 2021).
McLeod syndrome (3 papers, 2024 to 2025). "Subsequent genetic testing revealed a pathogenic large deletion at Xp21.1-p11.3, encompassing multiple OMIM Morbid genes, including DMD, Cilia- and flagella-associated protein (CFAP47 infertility), and XK (McLeod syndrome)." (PMID 40745660, 2025). "Given that some patients with McLeod syndrome harbor mutations in OTC and DMD, the secondary pathology may arise from mutations in genes contiguous to the primary causative gene." (PMID 39000307, 2024). "In some patients with McLeod syndrome due to large deletions, VPS13B and DMD may be lost." (PMID 41190063, 2025).
neuroblastoma (3 papers, 2012 to 2021). Neuroblastoma (NB) is the most common solid, extracranial childhood tumor. "Other studies have investigated the role of DMD gene deletions in neuroblastomas using patient samples." (PMID 33188621, 2021). "Similarly, DMD transcripts of SH-SY5Y neuroblastoma cells showed retention of part of intron 40, suggesting that alternate splicing of this intron is specific to cancer cells." (PMID 28546788, 2017).